DDR1 (discoidin domain receptor tyrosine kinase 1)
Diseases named in the same sentence as DDR1 in open-access papers (continued):
Sharing a sentence is not in itself a finding about the gene and the disease.
acute myeloid leukemia (9 papers, 2014 to 2025). Acute myeloid leukemia (AML) is a group of neoplasms arising from precursor cells committed to the myeloid cell-line differentiation. "For example, elevated DDR1 expression was significantly correlated with poorer prognosis in acute myelogenous leukemia (AML) but better prognosis in multiple myeloma (MM)." (PMID 35935941, 2022). "It is intriguing to consider the possibility that podocalyxin and DDR1 may be mechanistically linked given that their expression is coordinately suppressed by miR-199b-5p, a microRNA whose loss leads to the elevation of both DDR1 and podocalyxin in acute myeloid leukemia." (PMID 26796961, 2016). "A positive correlation was detected between DDR1 and tumor mutational burden (TMB) in testicular germ cell tumors (TGCT), STAD, and LUSC, and between DDR1 and microsatellite instability (MSI) in STAD and acute myeloid leukemia (LAML)." (PMID 40869052, 2025). "Moreover, miR-199a-5p inversely correlated with DDR1 expression in several tumors including cancers from breast, lung, ovary, thyroid, endometrium and acute myeloid leukemia." (PMID 26655502, 2016). "Previously, we showed that discoidin domain receptor 1 (DDR1), a class of collagen-activated receptor tyrosine kinase (RTK) was highly upregulated on bone marrow (BM)-derived CD33+ leukemic blasts of acute myeloid leukemia (AML) patients." (PMID 24519883, 2014). "Previously, we showed for the first time that discoidin domain receptor 1 (DDR1), a class of collagen-activated receptor tyrosine kinase (RTK), was highly upregulated on BM-derived CD33+ leukemic blasts of acute myeloid leukemia (AML) patients." (PMID 24519883, 2014).
pancreatic ductal adenocarcinoma (9 papers, 2015 to 2025). An infiltrating adenocarcinoma that arises from the epithelial cells of the pancreas. "Single-cell analysis in pancreatic ductal adenocarcinoma (PDAC) revealed DDR1-high ductal cells associated with reduced cytotoxic T cell infiltration and increased regulatory T cell populations." (PMID 40869052, 2025). "A recent study reported that increased DDR1 expression was linked to a poor prognosis in pancreatic ductal adenocarcinoma." (PMID 28143619, 2017). "In this study, we investigated the expression of DDR1 and its clinical association in Chinese patients with pancreatic ductal adenocarcinoma (PDAC)." (PMID 26297342, 2015). "The discoidin domain receptor 1 (DDR1) is activated in response to collagen degradation in other cancer sites such as pancreatic ductal adenocarcinoma, inducing aggressive biology in the presence of cleaved collagen." (PMID 41322090, 2025). "We subsequently focused on pancreatic ductal adenocarcinoma (PDAC) based on our pan-cancer analyses revealing DDR1’s pronounced impact in this malignancy, where it demonstrated the strongest association with immunosuppressive signatures." (PMID 40869052, 2025). "In pancreatic ductal adenocarcinoma, DDR1 activation by cleaved collagen leads to endocytosis and further catabolism of cleaved collagen." (PMID 41322090, 2025). "Pancreatic ductal adenocarcinoma (PDAC) emerged as a paradigmatic case of DDR1 dysregulation." (PMID 40869052, 2025). "This is consistent with previous reports that showed that the inhibition of DDR1 can improve the efficacy of chemotherapy in pancreatic ductal carcinoma and that the ectopic expression of DDR1 significantly increased the survival of lymphoma cells after chemotherapeutic drug treatment." (PMID 31717573, 2019). "COLVIII regulates various signaling pathways, including the interaction between DDR1 and COL VIII, which promotes pancreatic ductal adenocarcinoma progression, through PI3K-Akt and FAK-NF-κB upregulation." (PMID 39769286, 2024). "Furthermore, in pancreatic ductal adenocarcinoma, COL1 interacts with Discoidin Domain Receptor 1 (DDR1)." (PMID 39769286, 2024). "It has been shown that MMP-cleaved COL-I (cCOL-I) fibers promote pancreatic ductal adenocarcinoma (PDAC) bioenergetics and the tumor growth and metastasis, so that PDAC patients with over-expression of cCOL-I and lower expression of DDR1 showed poor survival outcomes." (PMID 39040062, 2024).
vitiligo (9 papers, 2013 to 2025). Generalized well circumscribed patches of leukoderma that are generally distributed over symmetric body locations and is due to autoimmune destruction of melanocytes. "This increases adherence to the basement membrane through contact with collagen I. Several studies showed that genetic variants of the DDR1 gene are associated with vitiligo, and the expression of DDR1 is decreased in vitiligo lesions." (PMID 37275386, 2023). "The DDR1 gene is located between the HLA-E and HLA-C genes at chromosomal region 6p21, previously linked to vitiligo susceptibility in a Chinese population." (PMID 24385829, 2013). "As genetic variants of the DDR1 gene are observed in Brazilian and Korean populations, dysfunction of DDR1 may be associated with vitiligo pathogenesis, although further functional analysis is necessary." (PMID 38673994, 2024). "A previous study highlighted the association between rs4618569 of the DDR1 and vitiligo development; the DDR1 gene seems to be an important player in immune responses, which depend on the effective migration of activated leukocytes into infectious or inflammatory tissue sites." (PMID 34071309, 2021). "DDR1 has additional roles in demyelination, fibrosis, vitiligo, and wound healing, and it is also a promising target for anti-fibrotic therapy." (PMID 38861581, 2024). "The keratinocytes in vitiligo lesions have a weaker expression of e-cadherin and Discoidin Domain Receptor tyrosine kinase 1 (DDR1), another molecule of cell-cell adhesion." (PMID 36754648, 2023). "In another study, imatinib has been proposed as a therapy for vitiligo because of its effects on the DDR1 gene." (PMID 24385829, 2013). "In humans, DDR1, XBP1, NLRP1 and PTPN22 genes have been linked to vitiligo and these genes could be a starting point to investigate if animals with vitiligo are linked to the genes and mutations reported in humans." (PMID 31324191, 2019).
liver cancer (8 papers, 2015 to 2025). An epithelial or non-epithelial malignant neoplasm that arises from the liver. "This phenomenon is more pronounced in liver cancer and likely explains the close association between DDR1 in serum and DDR1 in tumours." (PMID 37007062, 2023). "In liver cancer, the interaction between C1q, a component of the complement system, and DDR1 induces the upregulation of MMP2 and MMP9 expression, leading to migration and invasion." (PMID 33917302, 2021). "The results of the present study support the notion that C1q directly activates DDR1 in liver cancer cells and enhances migratory and invasive phenotypes." (PMID 29559654, 2018). "A strategy to selectively direct interventions to key driver genes such as DDR1 in PROM1+ TICs may be desired for the therapy for liver cancer." (PMID 33173221, 2020). "Our findings suggest that DDR1 may at least in part facilitate a potential tumorigenic link of PROM1+ cells to liver cancer." (PMID 33173221, 2020). "Finally, our studies open the door for future analyses on a role for DDR1 in other liver pathologies where excessive collagen is produced and the contribution of SCs is critical, such as fibrosis and primary liver cancer." (PMID 33110221, 2020). "So, we hypothesized that C1q might be a ligand of DDR1 (a known collagen receptor), and undertook this study, to investigate the molecular mechanisms of C1q and DDR1 in liver cancer cells." (PMID 29559654, 2018). "In liver cancer, CD44 binding to DDR1 enhances collagen-induced DDR1 signaling, promoting cancer stemness via the CD44/DDR1/YAP axis." (PMID 40563472, 2025). "In our study, DDR1 was identified as a tumor driver gene in PROM1+ subpopulation relevant to both mouse and patient liver cancer." (PMID 33173221, 2020). "Further, the treatment with the DDR1 inhibitor (DDR1in7rh), suppressed the growth of TICs at IC50 of 0.95 μM and that of the liver cancer cell line DIHXY at IC50 of 1.55 μM while PIL4 cells were four–fivefold less sensitive." (PMID 33173221, 2020).
metastatic tumors (8 papers, 2016 to 2025). "Abnormal DDR1 expression is detected in a range of solid tumors (including breast, ovarian, cervical, liver, gastric, colorectal, lung, and brain) and is associated with aggressive metastatic tumors (including breast and ovarian) and poor prognosis." (PMID 40603853, 2025). "Comparison of PDX tumors derived from metastatic or primary human PDAC tumors also revealed that PDX derived from metastatic tumors expressed higher levels of DDR1 than PDX derived from primary tumors." (PMID 34237033, 2021). "DDR1 also regulates invasiveness of patient‐derived CRC cell lines from metastatic tumours and circulating CRC cells and its expression level is associated with shorter overall survival in patients with mCRC." (PMID 29438985, 2018). "These in vitro results may explain the in vivo reduction of angiogenesis and tumor growth in the metastatic tumors of hepatic DDR1-silenced mice." (PMID 33110221, 2020). "Importantly, by bioinformatics approach, we were able to highlight a positive correlation between IGF-IR and DDR1 in expression data from several databases including the TCGA (The Cancer Genome Atlas) that comprises 522 primary tumors, 3 metastatic tumors, and 22 tumor-adjacent normal samples." (PMID 26655502, 2016).
breast tumor (7 papers, 2011 to 2024). "For instance, DDR1 has been involved in the collective migration of squamous cell carcinoma and breast tumor cells, metastatic reactivation in breast cancer, homing and colonization of lung and bones, and peritoneal metastases from gastric carcinoma." (PMID 32117772, 2020). "It is worth noting that the mRNA level of the pro-apoptotic mediator BIK was positively correlated to that of DDR1 in human basal-like breast tumors." (PMID 31130862, 2019). "DDR1 expression was then studied in a cohort of 3,951 breast tumors from patients where relapse free survival (RFS) was assessed." (PMID 31130862, 2019). "Basal-like breast tumors express significantly lower levels of DDR1 mRNA when compared to luminal A and B tumors." (PMID 31130862, 2019). "The expression level of apoptosis marker BIK was positively correlated to that of DDR1 in basal-like breast tumors (r = 0.2251, p = 0.0258)." (PMID 31130862, 2019). "Moreover, DARPP-32 re-expression inhibits migration in breast tumor cells through the mechanism of DDR1 and Thr-34 phosphorylation." (PMID 38308500, 2024). "Similarly, it was suggested that DDR1 promotes breast tumor growth by suppressing the anti-tumor immunity." (PMID 32117772, 2020). "Similarly, a neutralizing antibody against DDR1 inhibits breast tumor growth in a mouse model by suppressing the anti-tumor immunity." (PMID 32117772, 2020). "For instance, DDR1 activates, via a kinase-independent mechanism, Tuba and CDC42 to induce early proteolysis-based invasion of breast tumor cells." (PMID 32117772, 2020). "This agrees with the positive correlation observed between DDR1 and BIK expression in human basal-like breast tumors." (PMID 31130862, 2019).
oral cancer (7 papers, 2019 to 2025). "Taken together, these studies demonstrated that miR-486-3p and its host geneANK1 are epigenetically repressed in oral cancer through arecoline exposure, consequently causes the DDR1 expression." (PMID 31253192, 2019). "Indeed, TGFBI is one of the p-EMT hallmark proteins present in oral cancer tissues and is implicated in DDR1-mediated angiolymphatic invasions in the NCKU-OrCA-40TN cohort." (PMID 34869001, 2021). "The previous results have implicated DDR1 in cell proliferation and apoptosis in oral cancer cells." (PMID 31253192, 2019). "A previous report indicated that DDR1-IN-1 suppressed oral cancer cell growth and clonogenicity and inhibited the invasion of TW2.6 cells in vivo." (PMID 40603853, 2025). "Independently, our prior study showed that DDR1, COL4A5, COL4A6 and PDPN are statistically associated with angiolymphatic invasion in matched tumor-adjacent normal tissues from 40 Taiwanese oral cancer patients." (PMID 34869001, 2021). "miR‐486‐3p directly targets DDR1 mRNA 3′‐UTR to inhibit DDR1 expression, decreasing cell proliferation and enhancing apoptosis in oral cancer." (PMID 32368853, 2020). "Since DDR1 is a druggable target, our results provide an alternative therapeutic approach in blocking tumor cell growth and metastasis for oral cancer patients." (PMID 32244515, 2020). "In summary, our findings highlight amiR-486-3p/DDR1 axis, the dysregulation of which leads to the proliferation and survival of oral cancer." (PMID 31253192, 2019). "Whether the progression of oral cancer also involves similar pathologic interactions between DDR1 and type IV collagen is worth further investigation." (PMID 32244515, 2020). "Tyrosine kinase activity of DDR1 is required for both malignant functions; thus, clinically approved DDR1 kinase inhibitors could be considered as novel or adjuvant therapies for oral cancer treatments." (PMID 32244515, 2020). "Therefore, in the present study we sought to explore a miRNA-mediated molecular pathway leading to DDR1 dysfunctionin oral cancer." (PMID 31253192, 2019). "Re-expression of miR-486-3p in oral cancer through methylation inhibition may inhibit the proliferation activity of cancer cells byimpeding DDR1 expression." (PMID 31253192, 2019). "In this study, we found that arecoline treatment could recruit DNMT3B to ANK1 promoter and suppresses ANK1 and miR-486-3p expression, subsequently upregulated expression of DDR1 in oral cancer." (PMID 31253192, 2019). "This study was the first to demonstrate that betel nut alkaloid may recruit DNMT3B to regulate miR-486-3p/DDR1 axis in oral cancer andmiR-486-3p and DDR1 may serve as potential therapeutic targets of oral cancer." (PMID 31253192, 2019). "Furthermore, Kaplan-Meier analysis revealed that DDR1 expression was correlated with poor overall survival in oral cancer patients (n = 75) in our cohort (p = 0.0249) and in TCGA’s OSCC cohort (n = 163) (p = 0.0304)." (PMID 31253192, 2019). "Thus, abnormal repression of miR486-3p in oral cancer provides a growth advantage by enhancing the tumor promoting activities of DDR1." (PMID 31253192, 2019). "What’s more, discoidin domain receptor-1 (DDR1) could be activated by the specific binding with collagens (II,III), and the activation of DDR1 has been reported in oral cancer." (PMID 32571304, 2020). "Thus, DDR1 inhibitors are potential therapeutic compounds in restraining oral cancer, which has not been previously explored." (PMID 32244515, 2020).
Parkinson disease (7 papers, 2017 to 2025). A progressive degenerative disorder of the central nervous system characterized by loss of dopamine producing neurons in the substantia nigra and the presence of Lewy bodies in the substantia nigra and locus coeruleus. "Background/Objectives: We previously demonstrated that nilotinib can sufficiently enter the brain to pharmacologically inhibit discoidin domain receptors (DDR)-1 in patients with Parkinson’s and Alzheimer’s disease." (PMID 40565990, 2025). "The author's proposal was based upon their results showing that by inhibiting DDR1, the changes in brain tissue seen in Parkinson's diseases such as inflammation, neuronal injury, autophagy and vesicular transport are reversed." (PMID 34323026, 2021). "DDR1 inhibition stimulates clearance of neurotoxic proteins via autophagy in animal models of neurodegeneration and DDR1 is upregulated in post-mortem Parkinson’s disease (PD) and AD brains." (PMID 37194065, 2023). "Treatment of Parkinson’s patients (PD) with nilotinib, 150 mg or 300 mg, results in maximum cerebrospinal fluid (CSF) concentration (Cmax) of 1.9 nM and 4.12 nM, respectively, and a dose-dependent increase in DA levels; achieving a pharmacologically adequate concentration that would inhibit DDR1." (PMID 36557263, 2022).
renal fibrosis (7 papers, 2016 to 2024). A final common manifestation of a wide variety of chronic kidney diseases characterized by glomerulosclerosis and tubulointerstitial fibrosis. "Other investigators observed that in a model mimicking the Alport’s syndrome (COL4A3−/− mice), deletion of DDR1 delays renal fibrosis via inhibition of NF-κB, IL-6 and TGF-β signaling." (PMID 26880216, 2016). "This interaction between DDR1 and TGFβ1-Smad3 signaling can explain, at least partly, the decreased progression of renal fibrosis after the inhibition of DDR1 expression in the antisense groups." (PMID 26880216, 2016). "Moreover, lack of Ddr1 gene delayed the disease progression in Col4a3-/- AS mouse model, and pharmacological DDR1 inhibition suppressed albuminuria and renal fibrosis in Col4a3-/- mice." (PMID 33706638, 2021). "Since DDR1 has this dual function, a collage receptor which can activate inflammatory signaling pathways, we have investigated the involvement of DDR1 activation in mechanisms promoting renal fibrosis and inflammation." (PMID 26880216, 2016).
schizophrenia (7 papers, 2016 to 2024). A major psychotic disorder characterized by abnormalities in the perception or expression of reality. "According to a recent study, patients with schizophrenia who are carriers of the risk alleles for the DDR1 variant rs1264323 exhibit lower myelin integrity in brain regions associated with the cognitive processing speed." (PMID 36675255, 2023). "DDR1 gene variants were found to be associated with schizophrenia (SCZ) in candidate gene studies." (PMID 38395959, 2024). "DDR1 has been linked to schizophrenia (SCZ) and bipolar disorder (BD) in association studies." (PMID 38395959, 2024). "DDR1 was reported earlier as a susceptibility gene for schizophrenia and self-consciousness." (PMID 35215271, 2022). "Moreover, DDR1 is expressed in human oligodendrocytes and myelin, and variants in the human gene have been correlated with abnormal white matter and schizophrenia." (PMID 36355066, 2022). "Additionally, we identified an association between DDR1 genetic variants and schizophrenia." (PMID 36675255, 2023). "Genes previously showing strong genetic evidence implicated in schizophrenia identified in this study include: regulator of G-protein signaling 4 (RGS4); discoidin domain receptor family, member 1(DDR1); and the selenium binding protein 1(SELENBP1)." (PMID 26818902, 2016). "Previous studies have revealed that DDR1 is involved in schizophrenia (SCZ)." (PMID 34323026, 2021).
squamous cell carcinoma (7 papers, 2007 to 2025). A carcinoma arising from squamous epithelial cells. "DDR1 has also been shown to interact with Par3/Par6 at cell–cell contacts in A431 squamous cell carcinoma cell line." (PMID 30760555, 2019). "Normal epithelium showed weak cytoplasmic staining, whilst the majority of squamous cell carcinomas (8 of 12) showed increased DDR1 expression in comparison to adjacent normal epithelium." (PMID 31717573, 2019). "Involvement of DDR1 in regulating actomyosin contraction at adherens junctions has previously been suggested in squamous cell carcinoma A431 cells." (PMID 30760555, 2019). "Sahai and colleagues have demonstrated that the Par3 and Par6 polarity proteins generate contractile asymmetries in collectively migrating squamous carcinoma cells through their interaction with the collagen-binding Discoidin Domain Receptor 1 (DDR1)." (PMID 26796961, 2016). "The expression of DDR1 was significantly higher in squamous cell carcinoma than in adenocarcinoma (P=0.007; median expression 40.6 vs 23.1, respectively)." (PMID 17299390, 2007). "Moreover, the regulation of DDR1 levels and centrosome clustering by E-cadherin is maintained in cancer cells, as demonstrated by the CRISPR-Cas9 knockout of E-cadherin in the human squamous carcinoma line A431." (PMID 29133484, 2018).